INS (insulin)
Diseases named in the same sentence as INS in open-access papers (continued):
Sharing a sentence is not in itself a finding about the gene and the disease.
Obesity (continued). "Furthermore, the biological activity of cytokines that are increased during placental ischemia should be examined and whether this activity is exaggerated by obesity or specific metabolic factors such as high levels of leptin, cholesterol, fatty acids, insulin or glucose." (PMID 26569331, 2015). "In line, as Apoe−/− mice are protected from HFD-induced obesity, they display less hypertrophy of adipose tissue on HFD, lower inflammation levels and increased insulin sensitivity." (PMID 26695075, 2015). "These animals exhibit significant hypoglycemia upon starvation and after diet-induced obesity, supporting a physiological role of 11β-HSD1 in maintaining glucose production and/or inhibiting insulin secretion." (PMID 26305481, 2015). "There was a significant increasing trend in AEA, 2-AG, WC (P<0.001), insulin (P = 0.005), HOMA-IR (P = 0.004), leptin (P = 0.008), hsCRP (P = 0.002), along the three degrees of obesity." (PMID 26561012, 2015). "Altogether, these results demonstrate that TNK improved hyperlipidemia, obesity, IFG, IGT, insulin sensitivity and hypertension in SHR/cp rats." (PMID 25874615, 2015). "Blood pressure (SBP/DBP), insulin, HOMA-IR, LDL, TG, and the TG/HDL ratio significantly increased in both sexes, but the HDL significantly decreased as the children’s obesity increased." (PMID 25768006, 2015). "Insulin/IGF signaling, in cooperation with chronic low-grade inflammation, is also an important contributor to the cancer-promoting effects of obesity." (PMID 26029167, 2015). "Specifically, studies on Bag-1 and MK-5046 have demonstrated that these compounds stimulate an increase in glucose-mediated insulin secretion in insulinoma cell lines (INS-1 832/3 and MIN6), and in vivo, they also exert several anti-obesity effects." (PMID 25653074, 2015). "However, it is possible that the association of obesity with BMD is based in the conversion of androgen to estrogen, which improves bone mass in both males and females and maintains healthy plasma levels of insulin and regulating factors such as insulin-like growth factor-1, leptin, and adiponectin." (PMID 26090818, 2015). "For example, in the murine High-Fat diet induced model of obesity, treatment of mice with LNFPIII-NGC alleviated liver hepatosteatosis and improved insulin sensitivity in part, via a macrophage IL-10 dependent mechanism." (PMID 26340260, 2015). "Muscle cells which are an important reservoir for glucose become irresponsive to insulin in the presence of extreme amounts of FFA, TG and other lipid metabolites due to obesity and dyslipidemia." (PMID 26831558, 2015). "It has been previously shown that the teenagers with a high degree of obesity exhibited high blood concentrations of LDL-C, glucose and insulin." (PMID 26556365, 2015). "An examination of the relationships between the levels of CHP in obese women and parameters of insulin secretion (fasting C peptide/insulin molar ratio) further suggested a role for this peptide in HIC and hyperinsulinemia in obesity." (PMID 26703752, 2015). "Here, it was reported that adipose-derived tumour necrosis factor alpha (TNF-α) levels in mice were increased during the advancement of obesity, but when TNF-α was neutralised, insulin sensitivity was improved." (PMID 26257839, 2015). "In obesity, the expanding adipose tissue releases a large numbers of mediators, including TNF-α, IL-6, and MCP-1 as well as FFA, which can interfere with insulin signaling." (PMID 25816341, 2015). "We, along with others have shown that a high-fat diet induces obesity and metabolic abnormalities typical of DM2, elevated glucose, insulin and IGF-1 in these strains." (PMID 26641266, 2015). "Although ApoE-/-TSP1-/- mice developed similar level of obesity as ApoE-/- mice, ApoE-/-TSP1-/- mice had reduced systemic inflammation and improved glucose tolerance and insulin sensitivity." (PMID 25803585, 2015).
Obesity (continued). "Consistent with the study in a diet-induced obesity model, PM2.5 elevated blood glucose levels and impaired insulin signaling evidenced by reduced Akt phosphorylation in the genetic KKay mice." (PMID 24886175, 2014). "Our results are partly in line with the findings of other investigators who evaluated the effect of obesity and PCOS on glucose, lipid, and insulin metabolism (32, –, 34)." (PMID 24694334, 2014). "Pharmacologically, losartan normalized the glycemia and insulin changes due to obesity, but OBL sustained superior HOMA values and impaired insulin sensitivity, as seen by ITT's AUC in relation to CL." (PMID 24466104, 2014). "Although diet induced obesity is characterized by specific gut bacterial changes, whether acute IL-15 treatment in obese animals result in its own characteristic bacterial profiles and mediates the improved glucose and insulin responses have yet to be determined." (PMID 25517731, 2014). "We found no positive correlation between epicardial adipose tissue thickness and fasting glucose, insulin level, and HOMA-IR in obesity groups." (PMID 25755863, 2014). "Diet-induced obesity has been shown to impair AMPK regulation by leptin, insulin, and sympathetic neural efferent’s in other tissues, and aspects of AMPK function appear to be restored with weight loss." (PMID 24849657, 2014). "Herein, we presumed that glucose metabolism was altered by obesity in mice that fed on an HFD for 4 weeks and we therefore measured the blood glucose and serum insulin levels in all mice." (PMID 25237599, 2014). "Treatment of animals with recombinant adiponectin with obesity leads to decreased hyperglycemia and free fatty acids (FFA) in plasma and improves insulin sensitivity." (PMID 24410812, 2014). "Insulin sensitivity, however, improved significantly in the A-FABP knockout mice despite their obesity." (PMID 24842767, 2014). "In obesity, adipocytes can release pro-inflammatory mediators, such as quimiokine CC (CCL) -2, TNF-α and NEFAs instead of leptin and adiponectine that promote insulin sensitivity in a normal state." (PMID 25493077, 2014). "Insulin administration increases POMC mRNA expression while reducing NPY expression and protecting against diet-induced obesity." (PMID 25258479, 2014). "TNF-α is considered to be a possible therapeutic target because it was up-regulated in multiple rodent-obesity models and TNF-α blunted insulin signaling in insulin targeting tissues." (PMID 25077824, 2014). "All obesity group subjects had significantly higher total cholesterol (TC), triglycerides (TG), low-density lipoprotein cholesterol (LDL-C), insulin levels and HOMA-IR (all P<0.05)." (PMID 24475149, 2014). "Although there is minimal evidence on endocrine regulation in obesity after hemorrhage, there is ample data on obesity and exercise, another situation when SNA is elevated and insulin secretion is suppressed." (PMID 25472607, 2014). "Glucose metabolism, insulin, lipid, and ACE activity disorders observed with obesity were minimized by Losartan." (PMID 24466104, 2014). "Anthropometrics, laboratory and insulin metabolism related parameters of controls and PCOS patients according to the obesity status." (PMID 24705280, 2014). "According to our results, obesity in males led to a significantly higher levels of insulin, C-peptide, HOMA-IR and lower C-peptide to insulin ratio than in obese girls." (PMID 25419241, 2014). "We subsequently tested the effect of the insulin-sensitizing agent metformin, a widely prescribed medication that is considered first-line treatment for DM2, on our fly model of obesity and disseminated mucormycosis." (PMID 25268492, 2014). "The consequences of chronic AMIS are predictable and progressively lead to obesity at an early stage of the AMIS syndrome, and later to resistance to the direct action of insulin." (PMID 26237598, 2014). "We demonstrated that the fasting insulin levels and HOMA-IR progressively increased with increased obesity." (PMID 24137224, 2013).
Obesity (continued). "Strikingly, when exposed to high fat diet, obesity developed to a similar extent in JNK-1 mutants and controls and obesity induced a similar inhibition of insulin action in controls and mutants despite successful reduction of JNK-1 expression in these tissues." (PMID 23349837, 2013). "Obesity and high fat feeding mimic the effects of long-term incubation of islets with FFA on insulin secretion and Ca2+-channel distribution which correlate with an increased amount of fat within the islets and the surrounding exocrine pancreas." (PMID 23542897, 2013). "In the present study, the obese-fed rats developed obesity with low HDL-C as well as elevated BP, plasma glucose and insulin, which are considered as MS-related features." (PMID 23840732, 2013). "Similar to insulin, levels of IGF-1 correspond to energy status and are often elevated in obesity, possibly via hyperglycemia-induced suppression of IGFBPs synthesis and/or growth hormone receptor expression and IGF-1 synthesis." (PMID 23819063, 2013). "Thus, our current finding that isolated JNK overactivation and JNK-1 deficiency in skeletal muscle fails to protect from obesity-associated disturbances in overall glucose metabolism as assessed during glucose tolerance and insulin tolerance tests is surprising." (PMID 23349837, 2013). "Capsaicin also attenuates obesity-induced inflammatory responses by reducing TNF-α, IL-6, IL-8, and MCP-1 levels, while enhancing adiponectin levels, important for insulin response." (PMID 23698776, 2013). "Finally, after showing that DEP-1 was differentially regulated in metabolic tissues in diet-induced obesity, and that DEP-1 significantly impacts on insulin signaling, we addressed whether DEP-1 physically associates with the insulin receptor by recruitment studies applying PLA." (PMID 23889985, 2013). "Especially important to recognize are the links between insulin, glucose, and SREBP, suggesting an important role for SREBP in the pathology of current diseases, as obesity and the metabolic syndrome." (PMID 23516131, 2013). "The metabolic abnormalities associated with use of LHRHa have similarities to those in the metabolic syndrome: increases in obesity and concentrations of total and LDL cholesterol and triglycerides, and decreases in lean mass and insulin sensitivity." (PMID 23465742, 2013). "Reduced adiponectin levels such that accompany obesity, result in IGT due to reduced insulin sensitivity." (PMID 23675368, 2013). "Some of the pathways are related to obesity, such as the Jak-STAT-signaling pathway and the insulin-signaling pathway." (PMID 24339942, 2013). "In diet-induced obesity, overactivation of mTOR-S6K signaling favors expansion of the WAT mass, leading to insulin resistance of adipocytes through elevated serine phosphorylation of IRS1." (PMID 24391749, 2013). "Their results also showed the effect of DGAT1 on muscle insulin sensitivity and that DGAT1 transgenic mice were resistant to HFD (high fat diet) – induced obesity." (PMID 23642106, 2013). "As circulating concentrations of insulin and IGF-1 rise with increasing obesity, the levels of the sex hormone-binding globulins decrease." (PMID 23983688, 2013). "Specifically, whole-body PTP1B knockout (KO) mice are hypersensitive to insulin, lean and resistant to high fat diet (HFD)-induced obesity." (PMID 22509299, 2012). "IRS-1 is induced in high insulin conditions including the post-prandial state and obesity, whereas IRS-2 is increased in low insulin states such as fasting and caloric restriction." (PMID 22745692, 2012). "Waist circumference, the clinically accepted measure of obesity was significantly correlated with FPG, Insulin, IR, TBARS and TNF-α." (PMID 22860025, 2012). "A recent study reported a lean and obesity-resistant phenotype in the p/CIP single knockout mice, which exhibited increased insulin sensitivity and elevated energy expenditure due to increased PGC-1α expression and its decreased acetylation by GCN5." (PMID 22859932, 2012).
Obesity (continued). "However, adiponectin is known to have an insulin-sensitizing effect, acting through the AMP-activated protein kinase, so that the association with MS may (at least in part) be explained by the decreased adiponectin concentration that accompanies obesity." (PMID 22929809, 2012). "Our results therefore uncouple the adipogenic, lipogenic, and obesity-inducing activities of p/CIP and SRC-1 as PPARγ coactivators from their activities on insulin signaling through IRS1." (PMID 22859932, 2012). "In summary, our study demonstrates that PCN-mediated PXR activation prevented diet-induced obesity in AKR/J mice, decreased lipid accumulation and maintained insulin sensitivity." (PMID 22723881, 2012). "B1−/− mice are protected against obesity induced by HFD and insulin action in fat has been shown to be required for age-related and hypothalamic lesion-induced obesity." (PMID 23024762, 2012). "Hyperinsulinemia, accompanied by mild obesity in Wdr13 knockout mice appears to be reminiscent of MOR1 and chop knockout mice, where adiposity is enhanced by higher insulin secretion." (PMID 22715406, 2012). "Series of studies have shown that a positive correlation between low levels of serum 25-OHD3 and impaired insulin sensitivity, T2DM, hypertension, hyperlipidemia and obesity is exist." (PMID 23351271, 2012). "Thus, we conclude that kinin receptors are important for modulation of insulin secretion and for the preservation of normal glucose levels and hepatic functions in obese mice, suggesting a protective role of the KKS regarding complications associated with obesity and T2DM." (PMID 22829877, 2012). "Clinical studies among a variety of patient populations including those with DM, obesity, and stroke have successfully used ISI to evaluate a change in insulin sensitivity after undergoing drug treatment." (PMID 22676348, 2012). "Although contrasting the reports of increased circulating LPC in obesity and T2DM, these results are consistent with those of others who found that plasma LPCs were diminished in glucose intolerant and insulin resistant individuals." (PMID 22848500, 2012). "The MetS-BMI interaction was significant for fasting glucose, 2-hour plasma glucose, fasting plasma insulin and HOMA-IR, indicating that the metabolic consequences of obesity seem to be more adverse among individuals with MetS." (PMID 21962038, 2011). "Plasma FFAs are elevated in obesity and T2D, and lowering FFA levels increases insulin sensitivity, while raising FFAs increases insulin resistance." (PMID 22087313, 2011). "Individual mice with obesity (body weight > 48 g) and T2DM (abnormal fasting blood glucose and impaired glucose tolerance and insulin sensitivity) were randomized and fed with water as controls or with water containing GABA (2 mg/ml) for another 12 weeks." (PMID 21966503, 2011). "One commonly studied candidate gene for obesity, the leptin receptor gene (LEPR), is on a biologic pathway to obesity (leptin-insulin pathway)." (PMID 22028824, 2011). "IMTG content is increased in skeletal muscle of sedentary populations including individuals with obesity and T2DM and negatively correlates with insulin-stimulated glucose disposal." (PMID 21760887, 2011). "Clearly insulin and IGF-1 playmajor roles in cancer development and progression, especially in obesity and type 2diabetes." (PMID 23908801, 2011). "Using this diet-induced obesity paradigm, we first demonstrate that TSP1 deletion reduces inflammation and improves whole body insulin sensitivity in the obese state." (PMID 22039525, 2011). "More importantly, after the establishment of obesity and T2DM, oral treatment with GABA significantly reduced the gain in body weight and improved glucose tolerance and insulin sensitivity in mice." (PMID 21966503, 2011).
Obesity (continued). "The additivity in improvement of glucose homeostasis and in preservation of insulin sensitivity was proved previously using cHF+F+ROSI treatment and hyperinsulinaemic-euglycaemic clamps during development of obesity in mice." (PMID 22073272, 2011). "Insulin and FFA are two of the main peripheral signals proposed to be interwined with the impaired GH release observed in obesity." (PMID 21826141, 2011). "After this acute- term study, following only one meal, the authors rapidly suggested that because insulin and leptin (the main regulatory factors of food intake) were lower after fructose meals; they might increase caloric intake and ultimately contribute to weight gain and obesity." (PMID 21050460, 2010). "Lipid infusion increased plasma FFA to levels observed in obesity and T2DM and reduced insulin sensitivity by 27% (p = 0.01)." (PMID 20158910, 2010). "The degree of obesity, as reflected by BMI, was correlated to most of the blood parameters determined, in particular with HDL and insulin." (PMID 20687939, 2010). "We did find a modest effect of PNPLA1 on obesity and PNPLA3 on insulin sensitivity although these data need confirmatory studies." (PMID 19390624, 2009). "Insulin, which is increased in MC4R-/- mice with late-onset obesity, belongs to the factors that augment LH sensitivity of interstitial gland cells." (PMID 19309531, 2009). "The plasma levels of insulin and HbA1c correlated on the one hand significantly with PAI activity and tPA concentration, on the other hand also with indices of obesity." (PMID 19419582, 2009). "A QTL with logarithm of odds (LOD) score of 2.8 on chromosome 13p12 for the obesity-INS factor and one with a LOD of 2.6 on chromosome 11q24 for the lipids-INS factor were described for African Americans." (PMID 19038053, 2008). "In a previous study, in which we established the detection of insulin effects on cerebrocortical activity with MEG, we have shown that human obesity is characterized by a reduced cerebral insulin response." (PMID 18030331, 2007). "In another study, the Candesartan Role on Obesity and on Sympathetic System (CROSS), candesartan was found to have comparable BP lowering to HCTZ, but the ARB also had a significant benefit on insulin sensitivity." (PMID 17910747, 2007). "As intramyocellular lipid accumulation in muscle is a major contributor to both insulin resistance and whole body fat deposition, inhibiting IMCL gain should be a long-term goal for preventing obesity in human." (PMID 17183713, 2006). "Lastly, Akt activation in response to insulin is enhanced in S6K-null mice, thus implicating S6K1 in diabetes and obesity." (PMID 16404421, 2006). "If we assume that obesity and dyslipidemia have separate biochemical pathways for their expression, it appears that the presence of INS in both latent obesity and lipids factors may be an indication that INS is an important contributor and possibly a connector of pathways in the development of MetS." (PMID 16076393, 2005). "This is in turn consistent with the view that the anti-obesity effect of CLA and the initial decrease in insulin sensitivity is due to apoptosis of adipocytes." (PMID 15642120, 2005). "Given that ADH1B knockdown reduces insulin‐stimulated glucose uptake, its dysregulation in our study may reflect impaired insulin sensitivity, which is consistent with the reduced insulin‐stimulated VAT glucose uptake in obesity in our previous report." (PMID 41077621, 2026). "This suggests the potential to increase insulin-stimulated glucose uptake, with particular importance for models of non-insulin-dependent diabetes and obesity." (PMID 41590669, 2026). "Obesity is a major component of the metabolic syndrome and has been shown to contribute directly to hepatic steatosis through mechanisms involving increased free fatty acid (FFA) flux, insulin resistance, and proinflammatory cytokine production in MASLD." (PMID 41598496, 2026).